LINC00901 (long independently transcribed non-coding RNA 901)
Synonyms: TCONS_00005428; BC040587; LSAMP-AS4
Gene: Long non-coding RNA gene on chromosome 3 (116,921,431 to 116,932,238, forward strand). Ensembl gene ENSG00000242385.
Diseases named in the same sentence as LINC00901 in open-access papers:
LINC00901 is named in the same sentence as 5 diseases in open-access papers, as found by Europe PMC text mining. Sharing a sentence is not in itself a finding about the gene and the disease. The quoted sentences say what the papers report.
pancreatic cancer (1 paper, 2023). "The study also found that the abnormal expression of LINC00901 could promote the growth and invasion of pancreatic cancer cells." (PMID 37928532, 2023).
LINC00901 also shares sentences with these, for which no sentence is quoted: breast carcinoma (3 papers); tumor (3); cancer (1); osteosarcoma (1).